NLRP3 (NLR family pyrin domain containing 3)
Diseases named in the same sentence as NLRP3 in open-access papers (continued):
Sharing a sentence is not in itself a finding about the gene and the disease.
Behçet’s disease (10 papers, 2015 to 2025). "Padula and co-authors published the case describing a patient with Behcet’s disease with the variant in the NLRP3 gene." (PMID 39975544, 2025). "Moreover, Colchicine, used by the patient for Behçet’s disease, exerts anti-inflammatory effects via inhibition of the NLRP3 inflammasome and IL-1β signalling." (PMID 41025024, 2025). "Additionally, the activation of the Nlrp3 inflammasome and the maturation of IL-1β have been reported in the autoinflammatory uveitis, such as Behçet’s disease." (PMID 38802924, 2024). "Genetic variants of NLRP3 and NLRP1 gene were found in patients suffering Behçet’s disease." (PMID 35836195, 2022). "Both mRNA and protein levels of NLRP3, ASC, and Caspase-1 were shown to be upregulated in PBMC and in skin lesions of patients with Behcet’s syndrome, compared to healthy controls." (PMID 34572082, 2021). "Upon in vitro stimulation of PBMC with LPS/ATP, the mRNA and protein levels of NLRP3, ASC and/or Caspase-1 were significantly up-regulated only in PBMC from active Behcet’s syndrome patients compared to healthy controls." (PMID 34572082, 2021). "A recent study suggested that expression of NLRP3 and ASC were elevated at mRNA and protein levels in blood samples of patients with Behçet’s disease as compared to healthy subjects." (PMID 31551961, 2019). "Although this clearly indicates a significant role of NLRP3 inflammasome signaling in Behcet’s syndrome, no data is available about inflammasome activity within the aortic lesions of these patients, so far." (PMID 34572082, 2021).
bipolar disorder (10 papers, 2015 to 2025). A disorder of the brain that causes unusual shifts in mood, energy, activity levels and the ability to carry out day-to-day tasks. "Frontal lobe samples of patients diagnosed with bipolar disorder had higher levels of NLRP3, ASC, caspase-1, and pro-inflammatory cytokines than samples from the control group." (PMID 40002529, 2025). "The current study is the first to examine the role of NLRP3 in the animal model of bipolar disorder." (PMID 35676979, 2022). "The involvement of NLRP3 in major psychiatric disorders has been reported in patients with major depressive disorder and bipolar disorder." (PMID 34956329, 2021). "The frontal cortex, hippocampus, and basal ganglia tissue from young, male Sprague-Dawley rats who received intracerebroventricular (ICV) ouabain as a model of bipolar disorder or artificial cerebrospinal fluid (aCSF) were examined for NLRP3 utilizing protein immunoblot (Western) analysis." (PMID 35676979, 2022). "TSPO upregulation is concomitant with NLRP3 inflammasome activation in bipolar disorder." (PMID 33542692, 2020). "However, a postmortem study compared the expression of NLRP3-related protein in brain tissue from patients with schizophrenia and bipolar disorder in which increased level of NLRP3 was observed in patients with bipolar disorder, but not schizophrenia." (PMID 34956329, 2021).
carotid atherosclerosis (10 papers, 2017 to 2026). A thickening and loss of elasticity of the walls of carotid arteries that occur with formation of atherosclerotic plaques. "In addition, NLRP3 inflammasomes are closely associated with colchicine, IL-1β, and IL-6 and are thought to be potentially important targets for anti-inflammatory treatment of atherosclerotic heart disease." (PMID 33598482, 2020). "Consistent with previous works, our result showed that high expressions of NLRP3 inflammasome components such as c-caspase-1 and c-IL-1β were observed in carotid atherosclerosis." (PMID 35464766, 2022). "In support of this, both others and we have demonstrated enhanced NLRP3 inflammasome activation in carotid atherosclerosis." (PMID 29176764, 2017). "Moreover, we have demonstrated that cholesterol crystal-induced activation of NLRP3 inflammasomes are an important driver of both coronary and carotid atherosclerosis." (PMID 41543641, 2026). "Additionally, ER stress has been found to trigger the release of mitochondrial ROS and the production of NLRP3, thereby inhibiting NLRP3 inflammasome-mediated pyroptosis and improving atherosclerotic heart disease." (PMID 38378646, 2024). "Herein we extend these reports by demonstrating increased plasma levels of IL-27 in 140 patients with carotid atherosclerosis, and increased mRNA levels of IL-27 subunits and IL-27RA, as well as increased expression of IL-1β and NLRP3 within the carotid lesion from 159 patients." (PMID 29176764, 2017). "Although in vivo confirmation is needed, our results suggest that IL-27 could interact with the NLRP3 inflammasome also in patients with carotid atherosclerosis potentially contributing to plaque progression." (PMID 29176764, 2017). "In this study we investigated the expression of IL-27 and its receptor in patients with carotid atherosclerosis and if IL-27 could modulate the inflammatory effects of the NLRP3 inflammasome in vitro." (PMID 29176764, 2017). "Because little is known about the NLRP3 inflammasome, IL-1β and IL-18 in patients with T2DM and AS, here we performed a cross-sectional study investigating these inflammatory components in patients with T2DM complicated with carotid atherosclerosis (CAS)." (PMID 29151018, 2017).
celiac disease (10 papers, 2012 to 2024). An autoimmune genetic disorder with an unknown pattern of inheritance that primarily affects the digestive tract. "Single nucleotides polymorphisms (SNPs) in the NLRP1 gene may lead to an increased inflammasome activation, contributing, together with NLRP3, to a predisposition to Celiac disease." (PMID 39684769, 2024). "However, a significant amount of research remains to be performed on the genetic and functional aspects of NLRP3 inflammasome variants in the predisposition to the risk of celiac disease." (PMID 25788762, 2015). "In addition, the polymorphisms in NLRP3 and NLRP1 genes were associated with Celiac disease, suggesting their involvement in the predisposition to the disease." (PMID 39684769, 2024). "In conclusion, we propose that p31-43 plays a central role in the pathogenesis of Celiac disease at least in part via an intrinsic ability to form oligomers of polyproline II-like structures that self-assemble and drive an NLRP3-caspase 1 dependent innate immune response in the intestinal mucosa." (PMID 30761127, 2019). "In fact, an abnormal activation of NLRP1 and/or NLRP3 inflammasomes results in an altered activation of IL-1β and NF-κB, contributing to the lack of immune tolerance common in Celiac disease." (PMID 39684769, 2024).
diabetic encephalopathy (10 papers, 2018 to 2026). A brain disease that is characterized by functional impairment of cognition, cerebral signal conduction, neurotransmission and synaptic plasticity, and underlying structural pathology associated with diabetes. "A recent study found that administration of GAS inhibited ERS and reduced NLRP3 inflammatory bodies, improving cognitive dysfunction and depressive behavior in mice with diabetic encephalopathy." (PMID 31828147, 2019). "Although these data show a close relationship between diabetic encephalopathy and NLRP3 inflammasome activation, the mechanisms by which it is activated is still unclear." (PMID 30544722, 2018). "Taken together, this study demonstrates that Gas attenuates the diabetic encephalopathy by inhibiting ER stress and NLRP3 inflammasome activation." (PMID 30544722, 2018). "We also found inflammation and ER stress were associated with diabetic encephalopathy, as ER stress, TXNIP, and NLRP3 inflammasome is activated in the hippocampus, but Gas treatment could reverse these changes." (PMID 30544722, 2018). "Thus, NLRP3 can influence the development of neuron death, inflammation, and may have an impact on diabetic encephalopathy." (PMID 30544722, 2018). "However, the precise link between ER stress and NLRP3 in diabetic encephalopathy is still unknown." (PMID 30544722, 2018). "In view of the lack of an understanding about Gas in diabetic encephalopathy, this present study investigated inhibitory roles of Gas on ER stress and NLRP3 inflammasome activation." (PMID 30544722, 2018). "However, the link between NLRP3 inflammasome and ERS in diabetic encephalopathy is not clear." (PMID 33937267, 2021).
geographic atrophy (10 papers, 2013 to 2023). "Activation of the NLRP3 inflammasome was implicated in mediating the degeneration of the RPE in geographic atrophy, the late stage of dry AMD, and the development of choroidal neovascularization, the hallmark of neovascular AMD." (PMID 27788256, 2016). "However, NLRP3 expression has been associated with both geographic atrophy and neovascular AMD because it was detected in drusen and near the BM." (PMID 26153682, 2015). "In macular RPE tissue from donors with geographic atrophy that is associated with late AMD, an increase of NLRP3, ASC, Caspase-1, IL-1β, and IL-18 proteins was observed." (PMID 35805159, 2022). "Interestingly, it was found that there are increased level of NLRP3 protein, IL-1β and IL-18 mRNA in the RPE of donor eyes from individuals with geographic atrophy and neovascular AMD." (PMID 26504591, 2015). "Other reports investigating the role of inflammasome in the pathogenesis of AMD observed an increased content of NLRP3, ASC, Caspase-1, IL-1β, and IL-18 protein in RPE tissue from the macula region of donors with geographic atrophy (GA) compared to non-diseased controls." (PMID 35805159, 2022).
graft versus host disease (10 papers, 2015 to 2026). An immune system disorder that occurs after allogeneic hematopoietic stem cell transplant and is a reaction of donor immune cells against host tissues. "TMAO also aggravated graft versus host disease by activating NLRP3 inflammasome to polarize M1 macrophage." (PMID 40886370, 2025). "Many studies have indicated that NLRP3 inflammasome dysregulation is involved in several autoimmune and inflammatory diseases, as well as graft-versus-host disease (GvHD), and skin and corneal allograft rejection." (PMID 37716974, 2023). "Furthermore, such activation of NLRP3 inflammasome contributes to the induction of antigen-specific antitumour immunity and pathogenesis of graft-versus-host diseases." (PMID 28537251, 2017). "In addition, accumulating evidence indicates that activation of NLRP3 plays a pivotal role in the development of transplant complications in patients receiving hematopoietic stem cell transplantation (HSCT) including graft versus host disease, severe infections, and transplant-related mortality." (PMID 34769275, 2021).
necrotizing enterocolitis (10 papers, 2020 to 2025). Necrotizing enterocolitis (NEC) is a devastating disease that affects mostly the intestine of premature infants. "They studied the effect of blockage of NLRP3 inflammasome activation to detect if it can ameliorate acute inflammatory injury, brain injury, and long-term cognitive impairment induced by necrotizing enterocolitis in mice." (PMID 41149694, 2025). "Inhibiting HMGB1 could improve intestinal inflammation in necrotizing enterocolitis by inhibiting NLRP3 via the TLR4 signalling pathway." (PMID 35197507, 2022). "In necrotizing enterocolitis (NEC) models, upregulated HMGB1 and NLRP3 expression exacerbate intestinal inflammation." (PMID 41354099, 2025).
osteomyelitis (10 papers, 2021 to 2026). An acute or chronic inflammation of the bone and its structures due to infection with pyogenic bacteria. "Whether the NLRP3/IL-1β signaling pathway is involved in susceptibility to osteomyelitis due to NLRP3 polymorphism (rs10754558) is unclear." (PMID 39301021, 2024). "The findings suggest potential linkages between SNPs in genes such as IL-1, IL-6, IFN-γ, TNF-α, VDR, tPA, CTSG, COX-2, MMP1, SLC11A1, Bax, NOS2, and NLRP3 with the development of osteomyelitis." (PMID 39301021, 2024). "aureus is inadequately controlled by the NLRP3 inflammasome in macrophages and within the bone microenvironment.IMPORTANCEStaphylococcus aureus causes difficult-to-treat, long-lasting infections such as osteomyelitis." (PMID 42267988, 2026). "These cumulative findings suggest that IL-10 SNP rs1800871, through its ability to modulate IL-10 levels and further influence the activation of the NLRP3 inflammasome, may exert an influence on the progression of osteomyelitis." (PMID 39301021, 2024). "Current research has amassed increasing evidence suggesting that SNPs in various genes, including IL-1, IL-6, IFN-γ, TNF-α, VDR, tPA, CTSG, COX-2, MMP1, SLC11A1, Bax, NOS2, and NLRP3, may contribute to the development of osteomyelitis." (PMID 39301021, 2024). "The expressions of pyroptosis-related proteins, NLRP3, caspase-1, and GSDMD were significantly increased in mouse osteomyelitis model induced by Staphylococcus aureus and infectious bone fragments of patients with osteomyelitis." (PMID 33215255, 2021).
ovarian failure (10 papers, 2020 to 2024). "On the basis of these results, we hypothesize that aging is associated with increases in the expression of NLRP3 inflammasome components, which would cause ovarian dysfunction, but KRGSF ameliorates these changes." (PMID 32331214, 2020). "NLRP3 inflammasome, caspase-1, and IL-1β expression are increased in GCs of patients with early onset ovarian insufficiency, and the fertility of female mice can be improved by inhibiting the expression of the NLRP3 inflammasome." (PMID 39026050, 2024). "We have previously found that the activation of NLRP3 inflammasomes and thus enhanced ovarian fibrosis are important causal factors of PCOS ovarian dysfunction, but its upstream regulatory networks remain to be elucidated." (PMID 37525261, 2023). "An elevated level of NLRP3 proteins was observed in the ovary of female mice during reproductive aging and in granulosa cells from patients with ovarian insufficiency, while the genomic ablation or pharmacological inhibition of NLRP3 ameliorated fertility." (PMID 35883561, 2022). "Therefore, we hold the opinion that Mox inhibits TXNIP/NLRP3/caspase-1 signaling-medicated pyroptosis and alleviates ovarian failure in POF." (PMID 33613687, 2021). "There is a high level of NLRP3 expression in granulosa cells from patients with ovarian insufficiency, and the NLRP3 inflammasome has negative effects on female fertility." (PMID 38903689, 2024).
peripheral nerve injury (10 papers, 2015 to 2026). Injury to a peripheral nerve. "The neuroprotective effects of berberine were closely associated with suppression of inflammation following peripheral nerve injury; berberine achieved these effects by inhibiting NLRP3 activation-induced M1 macrophage polarization." (PMID 41399377, 2026). "We next further explored the role of the regulation of MAL and NLRP3 targeted by miR-331-3p in repair of peripheral nerve injury." (PMID 34150749, 2021). "We have used total knockout of NLRP3 in a model of peripheral nerve injury (SNI) and a model of acute and delayed inflammatory pain." (PMID 26218747, 2015). "Here we hypothesize NLRP3 inflammasome has a role in acute and chronic pain following peripheral nerve injury, as well as a role in IL-1β expression." (PMID 26218747, 2015). "Nevertheless, our results from microarray analysis further verified that miR-183 could affect the neuropathic pain by regulating the thioredoxin interacting protein (TXNIP)/NLR family pyrin domain-containing 3 (NLRP3) inflammasome axis in peripheral nerve injury." (PMID 32723328, 2020). "Peripheral nerve injury has been shown to induce spinal cord neurogliocyte activation in chronic neuropathic pain models and is closely related to TLR4‐mediated NLRP3 inflammasome activation." (PMID 38415918, 2024). "In the current study, we administered GAS directly into the IT space and used a peripheral nerve injury-induced neuropathic pain model to examine the effect of GAS and the involvement of NLRP3 inflammasome at spinal level." (PMID 38835032, 2024). "It seems that especially monocytes contribute to the observed induction of NAIP1, NAIP2, and Nlrp1 at day 1 after peripheral nerve injury, while resident macrophages induce the expression of NAIP1, Nlrp3, ASC, and MCP-1 1 day after injury." (PMID 26253422, 2015). "Mechanical allodynia and thermal hyperalgesia are not affected by NLRP3 deletion, which suggest that this inflammasome is not necessary for the development of neuropathic pain related to peripheral nerve injury." (PMID 26218747, 2015).
renal failure (10 papers, 2011 to 2025). "Hydroxychloroquine (HCQ) reduces renal insufficiency by downregulating NLRP3 inflammasomes activation mediated by CTSB and CTSL." (PMID 36209090, 2022).
staphylococcus aureus infection (10 papers, 2013 to 2024). An infectious process in which the bacteria Staphylococcus aureus is present. "Accordingly, T. crassiceps infection strongly evokes prostaglandin E2 (PGE2) in AAMs, which facilitate host colonization, and it was recently shown that PGE2 can activate NLRP3 in peritoneal macrophages during Staphylococcus infection." (PMID 38842647, 2024). "Knockout of NLRP3 resulted in the downregulation of inflammatory cytokine production in Staphylococcus aureus infection." (PMID 32508567, 2020). "It was also reduced following NLRP3 knocked down in the early stage of Staphylococcus aureus infection by siRNA in human monocytic cell line THP-1." (PMID 30635040, 2019). "Knocking down NLRP3 reduced NF-κB activation and cytokine induction in the early stages of Staphylococcus aureus infection." (PMID 25761061, 2015). "In addition, the latest research shows that Staphylococcus aureus infection activates NLRP3 inflammasome through Nek7 and K+ efflux signaling." (PMID 35350616, 2022). "Staphylococcus aureus infection of wounds upregulates keratinocyte IL-1 that drives neutrophil recruitment via IL-1R1 signaling, while NLRP3 activation is also seen after sterile burn injuries, with Nlrp3-/- mice showing reduced macrophage infiltration and impaired healing after chemical burns." (PMID 33391283, 2020).